SCN4B (sodium voltage-gated channel beta subunit 4)
Description:
Regulatory subunit of multiple voltage-gated sodium (Nav) channels directly mediating the depolarization of excitable membranes. Navs, also called VGSCs (voltage-gated sodium channels) or VDSCs (voltage-dependent sodium channels), operate by switching between closed and open conformations depending on the voltage difference across the membrane. In the open conformation they allow Na(+) ions to selectively pass through the pore, along their electrochemical gradient. The influx of Na+ ions provokes membrane depolarization, initiating the propagation of electrical signals throughout cells and tissues. The accessory beta subunits participate in localization and functional modulation of the Nav channels. Modulates the activity of SCN1A/Nav1.1. Modulates the activity of SCN2A/Nav1.2.
Synonyms: LQT10; ATFB17; Navbeta4
Tractability: Small molecule: a structure with a bound ligand is known. Antibody: UniProt places it where antibodies can reach, with high confidence; its Gene Ontology location is reachable by antibodies, with high confidence; UniProt predicts a signal peptide or a membrane-spanning region.
Safety:
Unwanted effects reported when the protein is acted on. In parentheses: how it was acted on, where the effect was seen, and who reports it.
agitation (inhibition, acute dosing; nervous system, respiratory, cardiovascular; source: Lynch et al. (2017))
cardiac arrhythmia (inhibition, acute dosing and activation, acute dosing; nervous system, respiratory, cardiovascular; source: Lynch et al. (2017))
coma (inhibition, acute dosing; nervous system, respiratory, cardiovascular; source: Lynch et al. (2017))
convulsions (activation, acute dosing; nervous system, respiratory, cardiovascular; source: Lynch et al. (2017))
decreased blood pressure (inhibition, acute dosing; nervous system, respiratory, cardiovascular; source: Lynch et al. (2017))
decreased cardiac conduction (inhibition, acute dosing; nervous system, respiratory, cardiovascular; source: Lynch et al. (2017))
decreased cardiac contractility (inhibition, acute dosing; nervous system, respiratory, cardiovascular; source: Lynch et al. (2017))
decreased gastrointestinal transit (inhibition, acute dosing; nervous system, respiratory, cardiovascular; source: Lynch et al. (2017))
decreased locomotor activity (activation, acute dosing; nervous system, respiratory, cardiovascular; source: Lynch et al. (2017))
decreased pain (inhibition, acute dosing; nervous system, respiratory, cardiovascular; source: Lynch et al. (2017))
decreased respiratory rate (inhibition, acute dosing; nervous system, respiratory, cardiovascular; source: Lynch et al. (2017))
decreased sweating (inhibition, acute dosing; nervous system, respiratory, cardiovascular; source: Lynch et al. (2017))
decreased urine excretion (inhibition, acute dosing; nervous system, respiratory, cardiovascular; source: Lynch et al. (2017))
decreased/increased convulsions (inhibition, acute dosing; nervous system, respiratory, cardiovascular; source: Lynch et al. (2017))
decreased/increased heart rate (inhibition, acute dosing; nervous system, respiratory, cardiovascular; source: Lynch et al. (2017))
dyspnea (activation, acute dosing; nervous system, respiratory, cardiovascular; source: Lynch et al. (2017))
increased heart rate (activation, acute dosing; nervous system, respiratory, cardiovascular; source: Lynch et al. (2017))
increased pupil diameter (inhibition, acute dosing; nervous system, respiratory, cardiovascular; source: Lynch et al. (2017))
increased QRS complex (inhibition, acute dosing; nervous system, respiratory, cardiovascular; source: Lynch et al. (2017))
Gene: Protein-coding gene on chromosome 11 (118,133,377 to 118,152,888, reverse strand). Ensembl gene ENSG00000177098.
Subcellular location: Cell membrane
Pathways (Reactome):
Developmental Biology: Interaction between L1 and Ankyrins
Muscle contraction: Phase 0 - rapid depolarisation
Sensory Perception: Sensory perception of sweet, bitter, and umami (glutamate) taste
Gene Ontology:
Molecular function: protein binding; sodium channel regulator activity; transmembrane transporter binding; voltage-gated sodium channel activity; voltage-gated sodium channel activity involved in cardiac muscle cell action potential
Biological process: AV node cell action potential; cardiac muscle cell action potential involved in contraction; cardiac muscle contraction; membrane depolarization during cardiac muscle cell action potential; neuronal action potential; positive regulation of sodium ion transport; regulation of heart rate by cardiac conduction; regulation of ventricular cardiac muscle cell membrane repolarization; sodium ion transmembrane transport; sodium ion transport; cardiac conduction; regulation of membrane potential
Cellular component: plasma membrane; voltage-gated sodium channel complex; cation channel complex; intercalated disc; membrane
Genetic constraint (gnomAD): Loss-of-function variants: 16 observed, 18.34 expected, observed/expected ratio (o/e) 0.87, 90% interval 0.59 to 1.32. The upper end of that interval is the gene's LOEUF score, 1.32, which puts it in group 5 of 6, group 1 being the genes least tolerant of losing a copy. Missense variants: 269 observed, 298.83 expected, observed/expected ratio (o/e) 0.9, 90% interval 0.81 to 1. Synonymous variants: 127 observed, 129.75 expected, observed/expected ratio (o/e) 0.98, 90% interval 0.85 to 1.13.
Gene-disease validity (ClinGen):
ClinGen rates the evidence that SCN4B causes each of these diseases.
long QT syndrome (autosomal dominant): Disputed.
Homologues: Orthologues: chimpanzee SCN4B (100% identical), macaque SCN4B (99% identical), mouse Scn4b (79% identical), rat Scn4b (78% identical), guinea pig SCN4B (68% identical), tropical clawed frog scn4b (49% identical), zebrafish scn4ba (46% identical), zebrafish scn4bb (41% identical). Paralogues in human: MPZL1 (23% identical), SCN2B (23% identical), JAML (22% identical), MPZL2 (22% identical), MPZL3 (21% identical), MPZ (20% identical).
Diseases named in the same sentence as SCN4B in open-access papers:
SCN4B is named in the same sentence as 54 diseases in open-access papers, as found by Europe PMC text mining. Sharing a sentence is not in itself a finding about the gene and the disease. The quoted sentences say what the papers report.
epilepsy (5 papers, 2019 to 2024). A brain disorder characterized by episodes of abnormally increased neuronal discharge resulting in transient episodes of sensory or motor neurological dysfunction, or psychic dysfunction. "SCN4B mutations are associated with a variety of diseases, including cancer, epilepsy, arrhythmia, sudden infant death syndrome, neuropathic pain, and various neurodegenerative diseases." (PMID 38877096, 2024). "POMC was also found to be co-expressed with SCN4B in our analysis, and it has been previously associated to epilepsy." (PMID 32331418, 2020).
breast carcinoma (4 papers, 2016 to 2024). "In breast cancer cells, decreased SCN4B protein expression correlates with high-grade primary and metastatic breast tumors and is also associated with enhanced breast cancer cell migration, invasiveness and metastatic spreading." (PMID 29723302, 2018). "In breast cancer cells, reduced SCN4B expression is associated with increased RhoA activity, enhanced cell migration and invasiveness, primary tumor growth and metastatic spreading, via promoting the acquisition of an amoeboid-mesenchymal hybrid phenotype." (PMID 29723302, 2018). "Emeline22 and others found that SCN4B expression was downregulated in breast cancer cells and promoted the migration and invasion of breast cancer cells through in vivo and in vitro experimental studies." (PMID 38877096, 2024). "In the first model, we assessed the importance of SCN4B expression in human breast cancer cells for the colonization of organs." (PMID 27917859, 2016). "One previous study reported that SCN4B is a metastasis-suppressor gene in breast cancer." (PMID 29723302, 2018). "Levels of SCN4B/β4 expression in mammary hyperplasia and dysplasia were similar to those recorded in normal mammary tissues, but were remarkably reduced in biopsies of mammary carcinomas." (PMID 27917859, 2016). "Correlatively, we found that SCN4B expression was higher in non-cancer epithelial mammary MCF-10A compared with several breast cancer cell lines such as MCF-7, MDA-MB-468, MDA-MB-435s and MDA-MB-231." (PMID 27917859, 2016). "Furthermore, SCN4B seemed to be the most significantly downregulated SCNxB gene in breast cancer tissues compared with non-cancer tissues." (PMID 27917859, 2016).
prostate carcinoma (4 papers, 2016 to 2024). A carcinoma that arises from epithelial cells of the prostate gland. "Two other genes that were found in this study to interact in association with GCNT1 are SCN2B and SCN4B, components of voltage-gated sodium channels, and both of these factors have been previously associated with the developing prostate cancer and promoting cancer metastasis." (PMID 32915819, 2020). "Knocking down miR-3175 in prostate cancer cells increased the SCN4B and E-cadherin expression, inhibited the N-cadherin expression, and importantly reduced cell proliferation, migration, and invasion." (PMID 34209614, 2021). "In prostate cancer cells, miR-3175 expression increases, and SCN4B expression decreases." (PMID 38877096, 2024). "However, after knocking down miR-3175, cell growth, migration, invasion, and N-cadherin expression, which are related phenotypes, are inhibited, and SCN4B expression is upregulated, suggesting that SCN4B may be a potential mechanism for miR-3175 to promote prostate cancer cell growth and invasion." (PMID 38877096, 2024).
Arrhythmia (3 papers, 2017 to 2024). Any cardiac rhythm other than the normal sinus rhythm. "Scn4a and Scn4b mutations and expression changes have been shown to be associated with arrhythmia and tightly regulated expression of these channels is required for physiological conduction." (PMID 32179820, 2020).
colorectal cancer (3 papers, 2020 to 2025). A primary or metastatic malignant neoplasm that affects the colon or rectum. "miR‐424‐5p was shown to promote proliferation and metastasis of colorectal cancer cells by targeting SCN4B and also to inhibit cell proliferation by targeting E2F7, Cyclin E1, Cyclin A2, and Cyclin D1." (PMID 40405535, 2025). "Additionally, in colorectal cancer, miR-424-5p has been shown to enhance cell proliferation and metastasis by directly targeting SCN4B." (PMID 39309825, 2024).
Long QT syndrome (3 papers, 2007 to 2015). "SCN4B forms a component of the sodium channel and has been associated with congenital long QT syndrome." (PMID 26001054, 2015). "A mutation in SCN4B resulting in a leucine to phenylalanine substitution at position 179 (L179F) was recently implicated as a putative cause of the congenital Long QT syndrome." (PMID 17623065, 2007).
atrial fibrillation (2 papers, 2011 to 2022). A disorder characterized by an electrocardiographic finding of a supraventricular arrhythmia characterized by the replacement of consistent P waves by rapid oscillations or fibrillatory waves that vary in size, shape and timing and are accompanied by an irregular ventricular response. "Some previous studies have established that genetic modification in sodium voltage-channel genes encoding for the cardiac β-subunits, such as SCN1B, SCN2B, SCN3B and SCN4B, can result in atrial fibrillation (AF)." (PMID 36362949, 2022).
cervical cancer (2 papers, 2016 to 2018). A primary or metastatic malignant neoplasm involving the cervix. "In cervical cancer tissues, SCN3B mRNA level is increased, whereas SCN1B, SCN2B and SCN4B mRNA levels are decreased." (PMID 29723302, 2018).
colon cancer (2 papers, 2013 to 2021). "In this study, the authors demonstrated that SCN4B was directly inhibited by miR-424-5p, thus promoting colon cancer cell proliferation, migration, and invasion." (PMID 34209614, 2021).
lung carcinoma (2 papers, 2016 to 2021). "In patient samples, SCN4B expression levels were downregulated in lung cancer compared with normal lung tissue, and preliminary immunohistochemical analyses in lung cancer tissue microarrays showed a tendency toward decreased protein expression in high-grade primary lung tumors and metastases." (PMID 33817575, 2021).
papillary thyroid cancer (2 papers, 2018 to 2019). "In this study, we aimed to explore the expression profiles of SCN4B in papillary thyroid cancer (PTC) and its prognostic value in terms of recurrence-free survival (RFS) in classical PTC." (PMID 29723302, 2018). "In addition, in papillary thyroid cancer SCN4B was downregulated at both RNA and protein levels in comparison with normal thyroid tissues, and sustained SCN4B expression was an independent indicator of favourable recurrence-free survival." (PMID 31661908, 2019).
schizophrenia (2 papers, 2022 to 2023). A major psychotic disorder characterized by abnormalities in the perception or expression of reality. "It is of interest to investigate the potential correlation between the higher Scn4b expression and the hypoexcitability in PV interneurons, and how they underlie the schizophrenia phenotype." (PMID 37545878, 2023). "Mutations in the most discriminative gene, Sodium Voltage-Gated Channel Beta Subunit 4 (SCN4B), may help understand cardiovascular associations with schizophrenia and its treatment." (PMID 35073334, 2022). "The voltage-gated sodium channel β subunit 4 (Scn4b) is expressed higher in PV interneuron and serves as a marker in the dorsolateral prefrontal cortex for schizophrenia." (PMID 37545878, 2023). "Our top-ranked gene, Sodium Voltage-Gated Channel Beta Subunit 4 (SCN4B), has not been associated with schizophrenia, but voltage-gated sodium channels have broadly been implicated in its pathogenesis." (PMID 35073334, 2022).
thyroid cancer (2 papers, 2021 to 2024). "The expression of SCN4B in the tissues of thyroid cancer patients is down-regulated, and SCN4B expression is an independent predictor of good relapse-free survival in thyroid cancer patients." (PMID 38877096, 2024).
adenomyosis (1 paper, 2020). The growth of endometrial tissue inside the muscular wall of the uterine corpus. "Additionally, sodium channelβ-subunit 4 (SCN4B) mRNA was decreased, suggesting possible regulation of m6A RNA methylation regulators to cell adhesion in adenomyosis." (PMID 32719721, 2020). "Possible target genes, including cadherin 3(CDH3), sodium channelβ-subunit 4 (SCN4B), and placenta-specific protein 8 (PLAC8), which are involved in cell adhesion, muscle contraction and immune response in the myometrium of adenomyosis patients were also validated." (PMID 32719721, 2020).
Ataxia (1 paper, 2020). Ataxia refers to impaired coordination of voluntary muscle movement. "A bioinformatic analysis across multiple datasets also indicated that expression of Scn4b was associated with a variety of ethanol-related traits (ethanol consumption, hypothermia, ataxia) in the BXD RI panel." (PMID 33066036, 2020). "Functional validation did not support the role of Scn4b in ethanol consumption, ataxia, or hypothermia." (PMID 33066036, 2020).
breast tumours (1 paper, 2016). "The most important reductions in SCN4B/β4 expression were observed when comparing in situ grade I to invasive grade II breast tumours." (PMID 27917859, 2016).
cardiac hypertrophy (1 paper, 2020). "As a main result we found that AGAT−/− mice exhibited altered gene expression related to energy metabolism (Fbp2, Ucp2), cardiac hypertrophy and fibrosis (Nppa, Ctgf), immune response (Fgl2), and the conduction system of the heart (Dsc2, Ehd4, Hcn2, Hcn4, Scn4a, Scn4b)." (PMID 32179820, 2020).
cognitive diseases (1 paper, 2020). "Furthermore, SCN2B and SCN4B were also identified in two studies for their potential effects in the neuronal development, brain functions and cognitive diseases." (PMID 32915819, 2020).
congenital long-QT syndrome (1 paper, 2022). "The differentially expressed genes included several causative genes of congenital heart defects, hypertrophic cardiomyopathy, congenital long-QT syndrome, muscular dystrophy, and dilated cardiomyopathy (e.g., Acta2, Ankrd1, Scn4b, Ano5, Rpl3l, Cenpf)." (PMID 35942699, 2022).
esophageal carcinoma (1 paper, 2024). A primary or metastatic malignant neoplasm involving the esophagus. "GABRG2, CNTNAP2, and SCN4B in the hub genes have high diagnostic value in determining whether hypopharyngeal carcinoma patients have combined esophageal carcinoma (AUC: 0.944, 0.944, 0.972)." (PMID 38877096, 2024).
gastric cancer (1 paper, 2025). A primary or metastatic malignant neoplasm involving the stomach. "Further in-depth analysis indicated that the genus Abiotrophia was inversely associated with eosinophils, P2RY12, and SCN4B genes, and positively linked with LGR6 in LBMI gastric cancer patients." (PMID 40041144, 2025).
Huntington disease (1 paper, 2021). Huntington disease (HD) is a rare neurodegenerative disorder of the central nervous system characterized by unwanted choreatic movements, behavioral and psychiatric disturbances and dementia. "The variants in SCN4B have been shown to be associated with ventricular tachycardia, Huntington’s disease, and can be a new biomarker of aggressive cancers." (PMID 33902636, 2021).
lung adenocarcinoma (1 paper, 2023). A carcinoma that arises from the lung and is characterized by the presence of malignant glandular epithelial cells. "SCN4B encoding voltage‐gated sodium channel β subunit is regarded as metastasis‐suppressor gene, and it expresses higher in normal samples than lung adenocarcinoma (LUAD) samples." (PMID 37826914, 2023).
neuropathy (1 paper, 2023). A disorder affecting the nervous system that manifests with pain, tingling, numbness, and/or muscle weakness. "SCN3A c.2077A > G and SCN4B c.298C > T were novel for a painful and painless neuropathy, and classified as VUS." (PMID 37175987, 2023).
rectal cancer (1 paper, 2016). A primary or metastatic malignant neoplasm that affects the rectum. "SCN4B expression was also down-regulated in prostate, colon and rectal cancers compared with normal tissues." (PMID 27917859, 2016).
temporal lobe epilepsy (1 paper, 2020). A localization-related (focal) form of epilepsy characterized by recurrent seizures that arise from foci within the temporal lobe, most commonly from its mesial aspect. "Hence, the hypothesis was that SCN4B could be impaired in temporal lobe epilepsy with hippocampal sclerosis (TLE-HS)." (PMID 32331418, 2020).
Ventricular arrhythmia (1 paper, 2025). "For ventricular arrhythmia, many of the significant proteins identified by the diffusion algorithm are ion channel proteins, such as those that contribute to Ca2+ (CACNA1C, CACNA1C-IT2), Na+ (SCN3A, SCN1B, SCN4B, SCN10A), or K+ (KCNQ1, KCNE3, KCNH2) transport in the heart." (PMID 39954672, 2025).